IL6 (interleukin 6)
Diseases named in the same sentence as IL6 in open-access papers (continued):
Sharing a sentence is not in itself a finding about the gene and the disease.
tumor (continued). "IL‐6 can be secreted by other types of cells in the tumor microenvironment (TME) including macrophages, endothelial cells, and bone marrow mesenchymal cells." (PMID 28865178, 2018). "IL-6 and CSF-1 also induce mTOR activation, resulting in cell survival and growth of alternatively activated macrophages in the tumor microenvironment." (PMID 29422647, 2018). "Both IL-6 and IL-10 showed positive cytoplasmic staining in BC cells with a heterogeneous staining pattern between, as well as within, certain tumour cores varying from weak to intense." (PMID 29256156, 2018). "Proinflammatory cytokines, IL-1α, IL-6 and IL-8, activate the NF-κB signaling during tumor growth and metastasis." (PMID 30486830, 2018). "The secretion of IL-6 from tumor cells induces bone turnover and enhances osteoclastogenesis and osteoblast differentiation which in turn leads to production of IL-6 by osteoblasts and further stimulates tumor cell proliferation in a paracrine fashion." (PMID 30180883, 2018). "This pathway is known to regulate expression of the tumor-promoting cytokines, IL-1, IL-6, and TNF-α." (PMID 30298062, 2018). "IL6, can prevent dendritic cell maturation, prime tumor-specific T-cells via signal transducer and activator of transcription 3 (STAT3) signaling, inhibit NF-κB binding activity, and inhibit C-C chemokine receptor type 7 (CCR7) expression." (PMID 29486723, 2018). "When we plotted the relative level of IL6 expression against the relative level of ERβ expression in tumor samples, we observed a significant positive linear correlation between ERβ and IL6 expression (R2 = 0.6507, P = 0.003)." (PMID 29970138, 2018). "Due to it pleiotropic activity, IL-6 is often synthesized by tumor cells, which leads to increased tumorigenesis and the formation of a tumor microenvironment that further enhances malignancy and decreases the effectiveness of therapies." (PMID 30283098, 2018). "As such, we investigated the tumoural source of IL-6 in sorted populations of cells from 4T1 tumours and identified that Il6 expression was restricted to the stroma in this model, with the TAMs expressing the highest levels." (PMID 30054470, 2018). "Our study demonstrates that MMP expression is regulated by local tumor cell density through the synergistic paracrine signaling of IL-6 and IL-8." (PMID 30220965, 2018). "In fact, blockade of IL-6 trans signaling by the designer cytokine sGP130Fc prevents tumor proliferation and angiogenesis in HCC at least in part via its inhibitory action on Stat3." (PMID 30224299, 2018). "But surprisingly, we found that e-MDSCs exposed in high IL-6 expressing tumor microenvironment presented SOCS3 suppression and sustained activation of JAK/STAT, while IL-6 short stimulation caused temporary SOCS3 regulation and JAK/STAT activation." (PMID 30083161, 2018). "The effect of EC stimulation with IL-6, and IL-10, on tumour–endothelial cell adhesion was investigated in this study." (PMID 29256156, 2018). "All above data showed that SOCS3 suppression and sustained activation of STAT3 occurred in e-MDSCs, which were correlated with tumor-derived IL-6." (PMID 30083161, 2018). "There is evidence that human endothelial cells, key players in tumor angiogenesis, can secrete even higher levels of IL-6 than tumor cells." (PMID 29351275, 2018). "At a systemic level, the tumour‐induced IL6 cytokine axis elevated circulating cholesterol levels by inducing host adipose lipolysis and hepatic cholesterol biosynthesis." (PMID 29540470, 2018). "Preclinical studies of inflammatory breast cancer have demonstrated enhancement of angiogenesis, metastasis, and invasiveness due to IL-6 secretion by M2 TAMs, resulting in accelerated tumor growth." (PMID 29862083, 2018). "Interleukin-6 (IL-6) is a crucial cytokine, which acts in angiogenesis, owing to fast tumor neovascularization." (PMID 30413047, 2018).
tumor (continued). "Adipocytes are known to play a significant role in promoting tumor progression by secreting cytokines including IL-6, IL-1, IL-8, and TNF-α." (PMID 30134951, 2018). "Elevated IL-6 levels in many kinds of cancer cells and in their tumor microenvironments were attributed to the activation of NF-κB signaling." (PMID 30405034, 2018). "We combined meticulous in vitro profiling and tumor xenograft models to study the role of IL-6 in MSC/OCC intereactions." (PMID 29455640, 2018). "Tumor-secreted factors such as IL-6 and parathyroid hormone-related peptide (PHRP) can stimulate browning, resulting in the increased energy expenditure of adipose tissue contributing to cancer-associated cachexia." (PMID 29805773, 2018). "IL-6 and TGF-β1 are important inflammatory mediators that have been implicated in tumour metastasis and the triggering of EMT, and they have been identified in proteins secreted by activated hepatic stellate cells." (PMID 30393774, 2018). "NF-κB plays a pivotal role in linking chronic inflammation to cancer development through its ability to upregulate several inflammatory and tumor promoting cytokines such as IL-6, IL-1α, and TNF-α, as well as survival genes such as BCL2 and BCLXL." (PMID 29772687, 2018). "Of note, tumour numbers were only reduced in tendency upon neutralisation with anti-IL-6 in lean and obese mice." (PMID 29695802, 2018). "The tumor cells can increase peripheral platelet count via thrombopoietin, IL-6 or leukemia inhibitory factor." (PMID 30103707, 2018). "Among tumor-secreted pro-osteolytic molecules, there are PTHrP, Interleukin-6 (IL-6), IL-1, Tumor Necrosis Factor α (TNFα), IL-8, IL-11, M-CSF, TGF-β, Vascular Endothelial Growth Factor (VEGF), Matrix metalloproteinases (MMPs), and prostaglandins." (PMID 29890702, 2018). "IL-6 is a pluripotent cytokine that can stimulate B-cell proliferation and differentiation, foster cell survival, and promote tumor growth." (PMID 30873511, 2018). "This interaction leads to adipocytes with an activated, tumor supportive phenotype characterized by lipolysis, a decrease in adipocyte markers and an overexpression of pro-inflammatory cytokines like IL-6 and IL-1β." (PMID 29930291, 2018). "We found that both granulocyte colony-stimulating factor (GCSF) and interleukin-6 (IL-6) were highly upregulated in the blood of PyMT-B6 tumor-bearing mice relative to tumor-free controls." (PMID 29593283, 2018). "The results showed that the mRNA levels of IFN-γ and PD-L1 in the tumor of the siRNA groups had significantly increased compared with the control group (p < 0.05).Survivin and IL-6 expression had decreased (p < 0.05)." (PMID 30564277, 2018). "HIF-1α significantly increased the expression of programmed cell death ligand 1 (PD-L1) and the secretion of IL-6, IL-10, and TGFβ1 in MDSCs in tumor bearing mice." (PMID 29682521, 2018). "IL-1β, which is secreted by pro-inflammatory macrophages, activates NFκB signaling within tumor cells which, among other effects, upregulates IL-6 production thereby establishing a positive regulatory feedback loop for maintaining cells in a stem-like state." (PMID 29883385, 2018). "tumor-derived microvesicles from several tumor cell lines modulate synthesis of interleukin-6 (IL-6) in MDSCs via the activation of Toll-like receptor 2 through the membrane-associated heat shock protein 72 (HSP 72)." (PMID 29868251, 2018). "Collectively, our in vivo data on IL6‐neutralising treatment suggest a complex pattern of response, with improved local tumour response and increased metastatic incidence." (PMID 29540470, 2018). "Rather, IL-6 acts on immune cells in the tumor microenvironment to promote inflammation and tumor growth." (PMID 30591653, 2018). "RANKL released from local osteoblasts stimulates the expression of interleukin 6 (IL-6) in the tumor cells." (PMID 30180883, 2018).
tumor (continued). "Consistent with an endometriotic tumor microenvironment, IL6 signaling was found to be increased in the primary tumors, peritoneal metastases, body fluids, and ascites." (PMID 30087267, 2018). "The release of interleukin IL-12 and IL-6 was enhanced by TLY-DCs at a ratio of 1 DC: 3 tumor apoptotic bodies (APO), however, the release of IL-10 was suppressed." (PMID 30081891, 2018). "We demonstrate that HO-1 expression, which is upregulated in response to the HWC IL-6, plays a role in facilitating transendothelial migration of tumour cells, thereby supporting their metastatic spread." (PMID 30054470, 2018). "Among its suppressive activities, IL-6 directly promotes cancer cell proliferation, survival and metastasis while indirectly supporting angiogenesis in the tumor microenvironment." (PMID 30348199, 2018). "It is worth pointing out that a tumour can trigger an inflammatory response, resulting in the release of proinflammatory cytokines such as IL-6 and IL-1β." (PMID 30539028, 2018). "Assessing only PFS, they found a tendency to longer PFS in patients with increased serum IL-6, but multivariate analysis showed that only tumor stage was an independent marker of PFS." (PMID 30038723, 2018). "Tumor-derived IL-6 has been shown to negatively regulate DC function by inhibiting their maturation and migration, affect the differentiation of hematopoietic progenitor cells from DCs to macrophage, and induce tolerogenic phenotypes of DCs." (PMID 30619378, 2018). "Specifically, the TCZ mediated reduction in IL-6-IL-6R signaling complexes decreases the pro-survival effects of IL-6, which results in an increase in the death rates of tumor cells." (PMID 29351275, 2018). "IL-6 is a known inducer of tumor-promoting inflammation that can activate a variety of proliferative cellular pathways including MAPKs, PI3Ks, and STATs, among others." (PMID 30613350, 2018). "Here we present a modeling framework that operates at both the cellular and molecular levels, for investigating IL-6 mediated, cancer stem cell driven tumor growth and targeted treatment with anti-IL6 antibodies." (PMID 29351275, 2018). "Tumour cell adhesion patterns to both IL-6 and IL-10 stimulated hMEC-1 and hTERT-LEC were unaltered." (PMID 29256156, 2018). "The robust suppression of T cells was recovered when IL-6R Ab or JSI-124 was administrated, which implied that tumor-derived IL-6 was the key trigger that regulated the development of competent e-MDSCs." (PMID 30083161, 2018). "The effects of IL6 stimulated by E2 on tumor growth were evaluated using a urethane-induced adenocarcinoma model." (PMID 29970138, 2018). "In order to further verify this fever‐like symptom on tumor‐bearing mice, the serum IL‐6 level of PCN and light‐treated PCN group was compared post‐treatment." (PMID 29938166, 2018). "After treatment there is an 80-90% decrease in the fraction of IL-6R occupied by IL-6 on tumor cells." (PMID 29351275, 2018). "Secretion of IL-17, G-CSF, IL-6 and SDF1in tumor microenvironment recruits CD11b+Gr1+ myeloid cells to tumor and conferring Bv8-associated VEGFR-independent angiogenesis leads to resistance to anti-VEGFR therapy." (PMID 29455658, 2018). "Neutrophils produce and secrete tumor-promoting growth factors, such as epidermal growth factor, vascular endothelial growth factor, interleukin (IL)-6 and IL-8, that can promote tumor cell activation and facilitate tumor development, invasion and metastasis." (PMID 29618336, 2018). "Immunoblot analysis of these tumors reveals that IL-6 deletion in ECs significantly reduced IL-6 expression in whole tumor lysates, confirming that ECs are one of major sources of IL-6 expression in GBM microenvironment." (PMID 29422647, 2018). "IL-6 has been reported to be critical in the tumorigenesis and tumor metastasis of epithelial cancer." (PMID 30369945, 2018).
tumor (continued). "We are currently modifying this model to describe xenografts that include human endothelial cells that have been demonstrated to produce IL-6 in greater amounts than tumor cells." (PMID 29351275, 2018). "As both IL-6 and collagen are highly abundant in healing wounds, these findings suggest that tumours can mimic a wound-like microenvironment which maintains an FAP+ HO-1+ TAM phenotype." (PMID 30054470, 2018). "As a typical biomarker of SASP, IL6 can activate immune responses, leading to improved clearance of senescent tumor cells, and stimulate proliferation of neighboring tumor cells." (PMID 30154433, 2018). "Several works have described that stromal IL-6 secreted by adipose cells can increase cell migration, invasion and tumor growth." (PMID 30123423, 2018). "The results revealed that treatment of IL-6 (100 ng/ml) significantly (p < 0.01) promoted tumor cell migration and invasion in RCC ACHN cells, while G3BP1 depletion strongly attenuated the IL-6-induced enhancement of RCC cell migration and invasion." (PMID 29717134, 2018). "With respect to human cytokines, only the inflammatory cytokines IL-6 and IL-8 were substantially secreted by SiHa tumor cells in the blood of mice." (PMID 29774117, 2018). "RDW elevation is strongly associated with the increase of other inflammation markers, such as interleukin-6 and tumor necrosis factor-α that can affect the tumor cell biological behaviors." (PMID 29643918, 2018). "In breast cancer cell lines, direct activation of β-adrenergic signaling can amplify expression of VEGF and cytokines, interleukin (IL)-6, and IL-8 that stimulate tumor angiogenesis." (PMID 29334991, 2018). "This study reveals that the expression of MMPs is tightly regulated by local tumor cell density through the synergistic signaling mechanism of Interleukin 6 (IL-6) and Interleukin 8 (IL-8) via the JAK2/STAT3 complex." (PMID 30220965, 2018). "In the TME, the presence of CAFs and their secretion of CCL2, CCL5, and CCL17 as well as the polarizing cytokines IL-1, IL-6, IL-13, and IL-26 can favor a tumor promoting TH2 and TH17 immune response, as the expense of tumor protective TH1 response." (PMID 29545811, 2018). "Under inflammatory conditions, immune cells and tumor cells release various inflammatory mediators, including interleukin-1β, interleukin-6, and tumor necrosis factor (TNF), which can suppress albumin synthesis in liver cells." (PMID 29685957, 2018). "These tumor-derived exosomes also increased the secretion of the pro-inflammatory cytokines IL-1β, IL-6, and IL-10, and decreased the release of IFNγ, IL-2, and IL-17, both in CD4+ and CD8+T cells." (PMID 29515996, 2018). "Tumor‐promoting inflammation is often mediated by the production of proinflammatory cytokines such as interleukin‐6 (IL6) (reviewed in Refs." (PMID 29987839, 2018). "Engrafted MM cells produced MC and IL-6, which correlated with the time from implantation and the tumor burden." (PMID 29732008, 2018). "Tumor derived IL-6 also acts as a chemoattractant to circulating tumor cells and facilitates self-seeding of disseminated tumor cells." (PMID 30081854, 2018). "In line with this evidence, expression of representative IL-6-mediated STAT3 target genes such as Socs3 and Timp1 were largely unaltered in tumor livers of lean IL-6Rα-deficient mice compared to controls." (PMID 30224299, 2018). "IL-6 plays diverse regulatory roles in cancer pathogenesis including remodeling the tumor microenvironment, activation of EMT process, and promoting drug resistance." (PMID 29898759, 2018). "HIC-1 plays a important role in the physiological regulation of multidrug resistance through the IL-6/STAT3 signal pathway, and has been implicated in the other various tumor." (PMID 30202238, 2018).
tumor (continued). "In particular, the pro-inflammatory cytokine IL-6 has been demonstrated to act as a key mediator in tumor cell growth by upregulation of metastatic gene expression and further stimulation of down-stream pro-inflammatory cytokines and growth factor release." (PMID 30081854, 2018). "Together, our findings support a notion that G3BP1 promotes tumor progression and metastasis through IL-6/G3BP1/STAT3 signaling axis in RCC." (PMID 29717134, 2018). "Tumor-associated fibroblasts (TAFs) promote tumor development by secreting cytokines as VEGF, IL-6, and HGF, that are responsible by the induction of the tumor vascularization and subsequently stimulate cell proliferation." (PMID 30304861, 2018). "A beneficial drug permeability effect of CCL2 or IL-6 must outweigh potential tumor stimulatory pathways." (PMID 30006619, 2018). "During oncogenesis, proinflammatory signals that are mediated by NF-κB, upregulate Lin28, which downregulates the tumor suppressor let-7 miRNA which targets IL-6." (PMID 29601548, 2018). "We collected both primary tumor tissue and metastatic lymph node tissue and measured ERβ/IL6 protein expression." (PMID 29970138, 2018). "Collectively, our data illustrate how tumour‐induced IL6 rewires host lipid metabolism to promote treatment resistance by fuelling tumoral androgen biosynthesis through enhanced cholesterol transport." (PMID 29540470, 2018). "These activated stromal cells, along with CD4+ T cells and myeloid-derived suppressor cells (MDSCs), are the main sources of IL-6 in most tumor microenvironments, alongside the tumor cells themselves." (PMID 30671025, 2018). "IL-17 in the TME in the CMS-G4 fibrosarcoma tumor model was largely derived from tumor-infiltrating γδT cells, and anti-cytokine mAb treatment revealed that the γδT cells require the presence of IL-6, IL-23, and TGFβ signaling." (PMID 29675018, 2018). "This modeling study not only quantifies the influence on IL-6 on primary tumor xenografts; it also provides some explanations for the various effects of TCZ on tumor growth and CSC percentage." (PMID 29351275, 2018). "Previous immunohistochemial studies with human GBM specimens suggest tumor-associated ECs and inflammatory cells as the major sources for IL-6 expression in the tumor microenvironment." (PMID 29422647, 2018). "EVs from heat-stressed tumor cells, which contain Hsp70, inhibit tumor growth by converting regulatory T cells to T helper 17 cells via Interleukin-6 (IL-6)." (PMID 29534557, 2018). "IL6 secreted by CAFs in hepatocellular carcinoma activates neutrophils in the tumor microenvironment, and induces PDL1 expression in them through the JAK-STAT3 pathway." (PMID 30380628, 2018). "High IL-6 expression independently predicts tumor recurrence, tumor metastasis and poor survival in head and neck cancer patients." (PMID 29351275, 2018). "Several tumor-derived factors, among which CSF3, IL-1β, and IL-6, have been implicated in recruitment, activation, and expansion of MDSCs." (PMID 29675018, 2018). "Another key cytokine, IL‐6, that plays an important role in tumor progression, was higher in 5/12 old KrasG12D mice when compared to average levels of IL‐6 in young KrasG12D mice (n = 14)." (PMID 29047229, 2018). "TAMs from SNAIL1 depleted tumors displayed increased expression of M1-like/anti-tumor genes like Ifna1, Il12a, Il6, Nos2, and Ifnb1." (PMID 29593211, 2018). "Another example includes the role of IL-6 in pituitary; while it enhances the proliferation of tumor cells, it also inhibits the growth of normal cells." (PMID 28740334, 2017). "IL-6 (+) tumor stromal cells were enriched together with EpCAM, K19 and CD133 expression (P <0.05 for all)." (PMID 28114366, 2017). "Neoplastic cells and tumor-associated macrophages (TAM) secrete IL-6, CSF-1, IL-10, TGF-β, TNF-α, IL-1α, angiogenic and lymphangiogenic growth factors that promote tumor development." (PMID 28830415, 2017).